CD34 (CD34 molecule)
Diseases named in the same sentence as CD34 in open-access papers (continued):
Sharing a sentence is not in itself a finding about the gene and the disease.
leukemia (continued). "They showed that LSC expressed a higher amount of CD82 than CD34+/CD38+ AML cells; these findings suggested that overexpression of CD82 may render LSC able to adhere to the bone marrow (BM) niche where it appears to regulate maintenance of leukemia stem cells within the BM niche." (PMID 28646224, 2017). "In addition, co-culturing ALL-MSC with the REH leukemia cell line, but not CD34+ hematopoietic progenitors, powerfully enhanced BMP4 production, suggesting an intimate crosstalk among ALL-MSCs isolated from BM colonized by ALL cells that presumably also occurs in situ conditions." (PMID 24400095, 2014). "It is known that progenitor cells (CD34+) in the bone marrow may express Fas in response to tumor necrosis factor-alpha (TNF-α) and interferon-gamma (INF-γ) in vitro and cytotoxic T lymphocytes in T-LGL leukemia may spontaneously produce INF-γ and TNF-α after stimulation." (PMID 18474096, 2008). "CD133 but not CD19 is expressed on normal primitive fetal hematopoietic stem cell/multipotent progenitors (Lin–CD34+CD38–), while fetal B-progenitors (CD34+CD19+) express CD19 but not CD133, confirming that CD133/CD19 coexpression is leukemia-specific." (PMID 40898981, 2026). "Strikingly, remission patients have much lower transition rates into the CD34+/CD38− and CD34−/CD38− cell states than corresponding samples from patients with leukemia not in remission." (PMID 41295979, 2026). "Data from primary CD45+ CD34+ CML blasts support this conclusion as they show that stroma increases mitochondrial dependence and non-glucose capacity in leukemia, while simultaneously decreasing glucose dependence and glycolytic capacity." (PMID 41331927, 2025). "Further immunophenotyping of these CD34+ MRD specimens indicated low expression or the absence of CD38 expression, which is consistent with an immature, leukemia-regenerating cell phenotype." (PMID 40609795, 2025). "They found the presence of such cells in the primitive CD34+ CD38- but not in the more mature CD34+ CD38+ fraction, suggesting that the leukemia clone is also organized as a hierarchy." (PMID 39272967, 2024). "Osimertinib, a third-generation covalent EGFR inhibitor, was shown to induce the apoptosis of the CD34+ leukemia stem and progenitor cells in EGFR-negative AML and CML, but no comparable cell death occurred in CD34− cells." (PMID 39518058, 2024). "The presence of the CD34+ antigen and the absence of CD38−, assessed by the authors, is taken into account in the identification of leukemia stem cells." (PMID 37675394, 2023). "When these CD25-positive and -negative populations were transplanted into the secondary recipient mice, both CD25-positive and -negative populations established leukemia in which the expression of CD25 and CD38 in Lin–CD34+ cells varied." (PMID 30550585, 2018). "Immunophenotyping by flow cytometry showed that leukemia cells were positive for CD13, CD33, CD64, CD38, CD9, cMPO, partial cells expressed CD117, whereas negative for CD5, CD19, CD34, HLA-DR, CD7, CD10, CD15, CD11b, CD14, CD56, CD20, GlyA, cCD79a, and cCD3." (PMID 30200136, 2018). "Ouabain, one of the CGs, specifically targeted CD34+CD38− leukemic stem-like cells, but not the more mature CD34+CD38+ leukemic cells, making this type of compounds a potential treatment for leukemia." (PMID 27110755, 2016). "We showed that this leukemia initiating cells subpopulation was not so rare in patients, and we found that FISH+CD34+CD38- cells ranged from 0.01% to 52.8% in the bulk of blasts." (PMID 24517186, 2013). "Although leukemia stem cells have been reported to increase in frequency during treatment in AML, CD34 and CD38 were not among the markers observed to increase, raising a further possibility that our choice of markers precluded the observation of treatment-based selection." (PMID 41295979, 2026).
leukemia (continued). "Interestingly, treatment with entinostat did not induce an increase in phospho-γH2A.X in healthy CD34+ cells (hCD34+), implying that disruption of the RUNX1/PTBP1 interaction induces double stranded breaks in leukemia cells, but not in healthy HSPCs." (PMID 41214140, 2026). "Similar to what is observed in mouse LICs, no obvious inward currents were elicited in CD34+-enriched human LICs at pH 7.4, pH 7.0, and pH 5.0, using whole-cell patch clamping, which indicated acid-ASIC3 exerted a noncanonical effect on leukemia development." (PMID 41392978, 2025). "The immunohistochemical study revealed that 90% of the CD20+ lymphoid cells were CD25+; Cyclin D1+ cells were positive in a small percentage of the leukemia cells; CD1a, TdT, and CD10 were not expressed by the bone marrow cells; and CD34+ cells were present in 1–2% of the blasts." (PMID 40126222, 2025). "Specifically, leukemic cells expressing HSC markers (e.g., CD34+CD38−), as opposed to the bulk of leukemia cells, generated blood cancers in mice after transplantation (with self-renewal inferred by the ability to serially transplant the leukemias from mouse to mouse)." (PMID 37832945, 2024). "In the 1990s, a detailed investigation of AML subpopulations provided the first proof of a rare LSC population, with a CD34+/CD38- phenotype, within AML capable of establishing leukemia in nonobese diabetic/severe combined immunodeficiency (NOD/SCID) mice: leukemic stem cells (LSCs)." (PMID 35800375, 2022). "In the case of CD34 negative AML, however, the leukemia-initiating cells are often contained within other immunophenotypic cell compartments, and in these AML subtypes, residual HSC may comprise the CD34+CD38− subset." (PMID 35892824, 2022). "Just a small fraction (0.01%) of human AML cells was able to initiate leukemia in nonobese diabetic-severe combined immunodeficient mice, their cell surface phenotype corresponded to that of a normal HSC (CD34++, CD38-), and, like HSCs, the cells that initiated leukemia were able to self-renew." (PMID 36362357, 2022). "Studies from Dick and colleagues were the first to support the hierarchical model of tumorigenesis by showing that sorted CD34+/CD38-, but not CD34+/CD38+ and CD34−, human acute myeloid leukemia (AML) cells injected in mice could give rise to leukemia." (PMID 33451077, 2021). "Interestingly, surface expression of Tim-3 was significantly elevated in CD34+CD38− AML leukemia stem cells (LSCs) and CD34+CD38+ leukemic progenitors, but not in CD34+CD38− normal HSCs or most portion of CD34+CD38+ normal progenitors." (PMID 31186046, 2019). "Building on seminal work by Lapidot and colleagues, which first established that CD34+ CD38−, but not blasts, from AML patients, constituted LSC and could initiate leukemia in xenotransplanted mice." (PMID 27597933, 2016). "Thus differences in leukemia development abilities between CD7+/CD34+ and CD7+/CD34− cells in fast growing T-ALL do not rely on distinct early homing properties." (PMID 27191650, 2016). "Importantly, FLT3 is expressed on leukemia blasts regardless of CD34 expression, whereas FLT3 expression is limited to the CD34+ population in normal human BM." (PMID 25295230, 2014). "In our RPPA on bulk leukemia cells in 511 newly diagnoses AML cases we observe that PU.1 expression was very heterogeneous in expression, with 30% of cases being above that of normal CD34+ cells and 26% being lower than normal CD34+ cells (data not shown)." (PMID 24223100, 2013). "TGF-β1 may promote the apoptosis of the CD34 and CD34-DR cells of patients with chronic myeloid leukemia; however, it does not increase the expression of the CD95 Fas receptor in leukemia cells." (PMID 23737898, 2013). "Despite the cytomorphological characteristics typical of APL, leukemia cells in the reported case lacked the signature characteristic immunophenotypic signs of malignant promyelocytes observed in APL, i.e., they were positive for HLA-DR, CD34 and brightly positive for CD117." (PMID 36980947, 2023).
leukemia (continued). "However, the leukemia initiating cells (LICs) which in this model share the immunophenotype of GMPs (Lineagelow, c-Kithigh, FcγRII/III+, CD34+) exhibited, contrary to non-neoplastic GMPs, markedly reduced pAktSer473 and pAktThr308 in response to stimulation with SCF." (PMID 34736527, 2021). "Furthermore, it was found that FLT3L CAR-T cells could activate the FLT3/ERK signaling pathway of FLT3+ leukemia cells with wild-type FLT3; meanwhile, it had no inhibitory effects on the colony formation of CD34+ stem cells derived from normal human umbilical cord blood." (PMID 29716633, 2018).
acute myeloid leukemia (308 papers, 1997 to 2026). Acute myeloid leukemia (AML) is a group of neoplasms arising from precursor cells committed to the myeloid cell-line differentiation. "Ex vivo expansion of human CD34+ hematopoietic stem/progenitor cells is a hallmark of distinct leukemic transcription factors found in acute myeloid leukemia." (PMID 38201282, 2023). "To assess the impact of cellular heterogeneity on expression biomarkers in acute myeloid leukemia, we systematically examined paired mononuclear cells and viable CD34-expressing leukemic blasts from SWOG diagnostic specimens." (PMID 36927800, 2023). "The number of CD34+ cells undergoing apoptosis is highest in low-risk MDSs (Lr-MDSs) and lowest after transformation into acute myeloid leukemia (AML)." (PMID 36902139, 2023). "Further, some studies have also assigned prognostic significance to CD34 as it is reported that the expression of CD34 is associated with good prognosis in acute myeloid leukemia." (PMID 33773558, 2021). "In addition, the dysregulation of PP2A in acute myeloid leukemia (AML) was associated with reduced B55α transcript levels compared with normal CD34+ cells." (PMID 41146310, 2025). "In the context of acute myeloid leukemia, for example, IL-1 secreted by monocytes and myeloid blast cells promotes the growth and clonogenic potential of pathogenic CD34+ cells while suppressing colony formation by WT CD34+ cells." (PMID 39545419, 2024). "CD34+/CD38− phenotype is linked to CSC in human acute myeloid leukemia." (PMID 23977261, 2013). "CD34+ cells isolated from the bone marrow of patients with Acute Myeloid Leukemia (AML) present low levels of ROS associated with quiescence, self-renewal, and chemotherapy resistance." (PMID 31781251, 2019). "A total of 525 adult patients (363 ATG, 162 CD34+) with intermediate or high-risk cytogenetics acute myeloid leukemia (AML) in first complete remission (CR1) were included." (PMID 30342553, 2018). "Acute myeloid leukemia (AML) is an immunophenotypically heterogenous malignant disease, in which CD34 positivity is associated with poor prognosis." (PMID 21595920, 2011). "Of note, four out of five patients with PV or ET who evolved to another haematological malignancy showed an increase in CD34-positive cell count at transformation (three secondary acute myeloid leukaemia and one chronic myelomonocytic leukaemia)." (PMID 41540281, 2026). "CD34+ AL cases were categorised as acute myeloid leukaemia (AML), acute lymphoid leukaemia (ALL) or acute unclassifiable leukaemia (AUL) by established FC criteria." (PMID 41137732, 2025). "Acute myelogenous leukaemia M0-2-like expressed markers of immaturity, 93% CD34, 100% CD117 and 93% HLA-DR positive, as well as other myeloid markers." (PMID 39968161, 2025). "Critical to CSC theory, John Dick’s team (1994) identified CD34+CD38− leukemia-initiating cells in acute myeloid leukemia (AML)." (PMID 41438763, 2025). "The initial modern identification of CSCs occurred through a CD34+/CD38− subpopulation of malignant cells being isolated from human acute myeloid leukemia (AML)." (PMID 38247819, 2024). "Patients with acute myeloid leukemia (AML), dry bone marrow aspirate, and CD34, CD117-negative blast cells can be in a diagnostic dilemma." (PMID 38933637, 2024). "Multiple studies on Acute Myeloid Leukemia (AML) have observed significant expression of PD-L1 on CD34+ blasts, CD4+/8+ T cells, and Tregs, particularly in bone marrow samples from R/R patients." (PMID 38627681, 2024). "Fecal and blood samples were collected from 14 healthy donors whose CD34+ HSPCs have been transplanted into patients with acute myelocytic leukemia (AML), acute lymphocytic leukemia (ALL) or myelodysplastic syndromes (MDS)." (PMID 38548771, 2024). "This review focuses on the genetic manipulation of human CD34+ primary hematopoietic stem/progenitor cells derived from healthy donors to model acute myeloid leukemia cell growth." (PMID 38201282, 2023).
acute myeloid leukemia (continued). "Propofol inhibited the differentiation capacity of acute myeloid leukaemia stem cells (CD34+/CD38− subsets)In presence of Propofol, the activity of Akt/mTOR, and the Wnt/β‐catenin pathways were diminished." (PMID 37156724, 2023). "Studies have not systematically compared the ability to verify performance of prognostic transcripts in paired bulk mononuclear cells versus viable CD34-expressing leukemic blasts from patients with acute myeloid leukemia." (PMID 36927800, 2023). "A recent study showed that inhibiting OGA promotes the differentiation of CD34+ hematopoietic stem and progenitor cells (HSPCs) and acute myeloid leukemia (AML) cells into DC via STAT3/5 signaling." (PMID 37675125, 2023). "Further, daunorubicin was reported to trigger strong upregulation of CRT on the surface of primary human CD34 acute myeloid leukemia (AML) cells, inducing ICD." (PMID 37153795, 2023). "Another FDA-approved IMS system is the CliniMACS CD34 Reagent System by Miltenyi Biotec utilizing the anti-CD34 for clinical allogeneic stem cell transplantation in patients with acute myeloid leukemia." (PMID 36826291, 2023). "H2O2 also enhanced the formation of TNTs and mitochondrial transfer from human bone marrow stromal cells (BMSCs) to CD34+ cells from patients with acute myeloid leukemia (AML), an effect relying on the NADPH oxidase-2 (NOX2)-dependent production of ROS." (PMID 35267518, 2022). "A study reported that Ventx was aberrantly expressed in CD34+ acute myeloid leukemia (AML), and its maximum expression was found in CD33+ myeloid cells but not in normal CD34+/CD38− leukemic cells." (PMID 35269883, 2022). "As previously reported, the immature KG1 acute myeloid leukemia cell line overexpressed LSC-associated and ABCB1 genes and made up an important CD34 + CD38− LSC subpopulation (10.4%)." (PMID 35628366, 2022). "In 1994 Lapidot and coworkers first identified a subpopulation of CD34+CD38−- CSCs in acute myeloid leukemia (AML)." (PMID 36230480, 2022). "Enoyl-CoA hydratase domain containing 3 (ECHDC3) increased in CD34+ progenitor cells of acute myeloid leukemia (AML) cells after chemotherapy." (PMID 36172164, 2022). "For example, targeting the overexpressed CD123 marker on CD34+ CD38− leukemic stem cells in acute myelogenous leukemia impairs leukemic stem cells homing to the bone marrow and induces a decrease in the overall AML cell repopulation." (PMID 35360863, 2022). "A 10-uL aliquot of magnetic beads coated with an anti-CD34 antibody, which is a unique marker of acute myeloid leukemia (AML), can isolate all the AML-specific exosomes from 100 to 1,000 μl AML plasma." (PMID 36051582, 2022). "The overexpressed level of Nanog has been reported in CD34+ acute myeloid leukemia (AML) cells of patients and LSCs cells." (PMID 35269883, 2022). "The impact of gene fusion in driving the leukemic transformation of primary human CD34 + hematopoietic cells in acute myeloid leukemia (AML) has been studied." (PMID 34617205, 2022). "The first isolation of CSCs by fluorescence-activated cell sorting using CD34 and CD38 (CD34+CD38−) surface marker expression was in acute myeloid leukemia and dates back to 1994." (PMID 33477367, 2021). "Comparison of the nuclear proteome and transcriptome of acute myeloid leukemia (AML) blast cells with CD34+ cells from healthy human identified eleven transcription factors with abnormal expression, and remarkably affected transcription regulation." (PMID 34063807, 2021). "The presence of CSCs has been demonstrated for the first time in human acute myeloid leukaemia as a CD34+CD38− population." (PMID 34075691, 2021). "We found that FASN mRNA levels were significantly higher in acute myeloid leukemia (AML) patients than in healthy granulocytes or CD34+ hematopoietic progenitors." (PMID 33742137, 2021). "CBFA2T3 depletion arrests cell cycle progression in acute myeloid leukemia cell lines and CD34 + hematopoietic stem and progenitor cells (HSPC)." (PMID 33743795, 2021).